TIGIT (T cell immunoreceptor with Ig and ITIM domains)
Diseases named in the same sentence as TIGIT in open-access papers (continued):
Sharing a sentence is not in itself a finding about the gene and the disease.
tumor (continued). "TIGIT, DNAM-1 (CD226), CD96, and CD112R are expressed on T cells and natural killer (NK) cells, while their ligands—CD155, CD112, CD113, and CD111—are expressed on APCs or tumor cells." (PMID 40356928, 2025). "Indeed, the top 30 significantly enriched immune modulators in ME patients included CCL8, a ligand for the tumour infiltrating Treg cells chemokine receptor CCR8, PVR, a ligand for the T cell checkpoint protein TIGIT and ITGA8, which is known to activate TGFb." (PMID 39915477, 2025). "The high-response group exhibited elevated expressions of BTLA, LGALS9, PDCD1LG2, TIGIT, TNFSF15, and VTCN1 compared to the low-response group, suggesting that patients with this tumor profile may benefit from ICIs therapy." (PMID 40761787, 2025). "Additionally, in anti-TIGIT antibody-treated spleens, there were more NK (CD3e–NK1.1+NKp46+) cells within the CD45.1+ tumor immune environment and concomitantly greater NK cell activation (as indicated by granzyme B expression) following anti-TIGIT treatment." (PMID 40111422, 2025). "TIGIT is increasingly expressed on exhausted and dysfunctional effector T cells and NK cells within the TME, primarily due to prolonged antigen stimulation and the immunosuppressive environment created by tumor cells." (PMID 40567374, 2025). "TIGIT and TIM3 are important immune checkpoint molecules, and blocking their signaling pathways can effectively restore the function of T cells and NK cells, enhancing anti-tumor immune responses, making them potential therapeutic targets for HCC." (PMID 40534863, 2025). "Moreover, in the healthy donor samples, it showed markedly lower expression of TIGIT, PDCD1, and CXCL13, indicating that this specific co-expression pattern is tumor-specific." (PMID 40799645, 2025). "TIGIT, DNAM-1, CD96, and CD112R are expressed on T cells and natural killer (NK) cells, while their respective ligands—CD155, CD112, CD113, and CD111—are expressed on APCs or tumor cells." (PMID 40356928, 2025). "Moreover, despite growing evidence that RNA modifications shape immune cell function and tumor immune evasion, their regulatory influence on immune checkpoint molecules such as CD70, CD80, and TIGIT remains largely unexplored." (PMID 40565233, 2025). "Studies have suggested that compared to Tregs in peripheral blood, tumor-infiltrating Tregs exhibit more proliferative and immunosuppressive phenotypes, with increased expression of CTLA-4, CD25, GITR, 4−1BB, OX40, ICOS, LAG-3, TIM3, TIGIT, and PD-1." (PMID 40587482, 2025). "The tumor-killing ability of NK cells improved with increasing concentrations of anti-TIGIT mAb, plateauing at 10 μg/mL with no further enhancement at 20 μg/mL." (PMID 40231264, 2025). "The NanoString tumor panel detected in treatment-naïve tumors of the L-TTF2 group higher immune infiltration (e.g., cytotoxic T-cells, B-cells) and checkpoint markers (e.g., PDCD1, CTLA4, TIGIT)." (PMID 40696453, 2025). "In addition, this molecule showed a positive correlation with the expression of PD-1, CTLA-4, TIGIT, LAG-3, and TIM-3, indicating its involvement in the immune exhaustion process in the tumor microenvironment." (PMID 40965626, 2025). "We observed that dual TIM3 and TIGIT KO in TILs augmented fold-expansion during the rapid expansion protocol (REP) as well as effector functions including cytokine production and serial killing upon co-culture with autologous patient-derived tumor cells." (PMID 41394272, 2025). "While Tex cells were also abundant in the primary tumor tissue, the expression of exhaustion genes (PDCD1, CTLA4, and TIGIT) was notably higher in liver metastasis (LM) tissue, suggesting that T cell functional exhaustion in the metastatic microenvironment contributes to immune evasion." (PMID 40303346, 2025). "With CD155 binding, TIGIT/CD96/CD226 transmits inhibition and activation signals to the immune system, and the integrated signals regulate immune functions and affect the anti-tumor immune response." (PMID 41181119, 2025).
tumor (continued). "TIGIT and CD96 are critical co-inhibitory receptors in tumor immune regulation." (PMID 39911397, 2025). "While anti-TIGIT monotherapy or combination therapy with anti–PD-1 has shown potential in some clinical trials, these approached remain insufficient to fully reinvigorate CD8+ T cells, particularly in patients with advanced or high tumor burden." (PMID 41268548, 2025). "Additionally, TIGIT+ Tregs enhanced the expression of the coinhibitory receptor T-cell immunoglobulin and mucin-domain containing-3 (TIM-3) within tumor tissue." (PMID 40567374, 2025). "Interestingly, known markers of activated (TIGIT, LAYN and HAVCR2) and tumor-reactive T cells (ENTPD1) were segregated into different clusters." (PMID 38724668, 2025). "Strategies under investigation include combination therapies with other immune modulators (e.g., LAG-3, TIGIT inhibitors), targeted therapies (e.g., EGFR or KRAS inhibitors), and epigenetic modulators that reprogram the tumor microenvironment to be more immunogenic." (PMID 41584608, 2025). "Within the tumor compartment, ILC1-like NK cells displayed the highest expression of PD-1, PD-1/TIM-3 co-expression, and TIGIT among all subsets, suggesting that this population may represent a uniquely dysfunctional or highly regulated NK cell state." (PMID 41268557, 2025). "In addition to this mechanism, CD47 overexpression blocks macrophage phagocytosis, checkpoint deletions (PD-1, TIGIT) prevent tumor-mediated suppression, and CISH knockout boosts cytokine signaling and persistence in the tumor microenvironment." (PMID 41487532, 2025). "Tumor CD8+ T cells were also most enriched with CD103+CD69+ resident memory T cells (Trm; 24.6% in tumor vs. 8.4% in MPE vs. 0.3% in blood) and exhibited the highest expression of the co-inhibitory receptors PD-1, LAG-3, TIGIT, and TIM-3." (PMID 41415427, 2025). "TIGIT, mainly expressed on exhausted CD8+ T cells, Tregs, and NK cells, interacts with a specific ligand on tumor cells, transmitting inhibitory signals through Immunoreceptor Tyrosine-based Inhibitory Motifs (ITIM) and Immunoreceptor Tyrosine-based Transferase (ITT) motifs." (PMID 41550427, 2025). "During the process of in vitro expansion and repetitive stimulation, along with the high concentrations of inhibitory cytokines in the tumor microenvironment, CAR-T cells develop an exhausted phenotype (upregulation of PD-1, LAG3, TIM3, and TIGIT and decreased secretion of IL-2, TNF-α, and IFN-γ)." (PMID 40002679, 2025). "Besides, TIGIT has been identified as a key receptor targeting CD155, a ligand broadly expressed on tumor cells, dendritic cells, and endothelial cells." (PMID 40747615, 2025). "Furthermore, significant differences in the expression of immune checkpoints—specifically CD200, CD274 (PD-L1), TIGIT, TNFRSF25, and TNFSF15—were observed between tumor and normal samples." (PMID 40666524, 2025). "These previous findings in other malignancies suggest that TIGIT, as part of the immunosuppressive TME, promotes tumor growth and could therefore be a prognostic and predictive marker, as well as a potential therapeutic target." (PMID 40822998, 2025). "Unlike PD-1/CTLA-4, inhibition of TIGIT in tumor therapy restores the immune function of T cells through multiple pathways." (PMID 40890162, 2025). "Although PD-1 and TIGIT are believed to regulate distinct coinhibitory receptors, studies have indicated that the inhibition of either PD-1 or TIGIT in preclinical tumor models was less effective in the absence of CD226." (PMID 39847233, 2025). "New IC molecules, including VISTA, TIM-3, LAG-3, TIGIT, programmed cell death ligand 2 (PD-L2), B7H3, BTLA and GITR, have been identified as potential targets for overcoming tumour heterogeneity and resistance, offering potential for more effective cancer immunotherapy." (PMID 40994140, 2025).
tumor (continued). "Furthermore, co-blocking TIGIT and PD-1 not only relieves the inhibition of CD226 by PD-1 but also restores CD226 functionality, significantly enhancing the anti-tumor response of immune cells." (PMID 41473772, 2025). "This suggests that TIGIT upregulation is an intrinsic immunoregulatory feature of the tumor microenvironment, rather than a reflection of tumor burden or progression stage." (PMID 40799645, 2025). "Similarly, TIGIT facilitates immune evasion by competing with CD115 for CD226 binding, while its ligand, CD155, overexpressed in GBM, enhances tumor migration and invasion." (PMID 39911397, 2025). "TIGIT blockade significantly suppressed tumor growth and reduced tumor mass compared to the control group, with no observable adverse effects, indicating its safety in this model." (PMID 40231264, 2025). "Furthermore, F. nucleatum binds to TIGIT and CEACAM1, inhibiting T-cell cytotoxic activity and protecting tumor cells from immune cell attack." (PMID 41011327, 2025). "Consequently, during radiotherapy, the ligands of NPC tumor cells bind to inhibitory receptors on NK cells, including TIM-3, LAG3, and TIGIT, thereby reducing NK cell cytotoxicity." (PMID 40936698, 2025). "However, despite comparable cell counts, the expression levels of TIGIT and TIM3 appeared stronger in p-αKO tumor sections." (PMID 40067762, 2025). "Notably, TIGIT-NECTIN2 interactions between T cells and tumor cells or antigen-presenting cells are more prominent than PD-1 signaling." (PMID 41514917, 2025). "While TIGIT expression does not vary significantly across tumor stages, its consistent upregulation in the tumor microenvironment suggests its utility as a predictive rather than prognostic biomarker." (PMID 40799645, 2025). "TIGIT delivers inhibitory signals to CD8+ T cells, which may somewhat weaken their anti-tumor activity." (PMID 41394809, 2025). "Tumor-specific CD8 + T cells exhibited higher expression levels of cytotoxicity-related genes IFNG and GZMK, immune regulators FOS and JUN, and exhaustion markers TIGIT and PDCD1." (PMID 39033098, 2024). "Though single targeting of TIGIT exhibited similar expression of PD-1, single targeting was not sufficient to elicit potent anti-tumor responses." (PMID 38429294, 2024). "Furthermore, inhibition of both TIGIT and PD-1 further promotes CD8+ T cell activation and improves survival in tumor-bearing mice." (PMID 39156900, 2024). "The combination of mIgG2a anti-TIGIT and anti-PD-L1 antibodies did not control tumour growth in FcγR-knockout mice, confirming a requirement for Fc–FcγR engagement for therapeutic activity of anti-TIGIT monoclonal antibodies in this model." (PMID 38418879, 2024). "Through scRNA-seq analysis in human tumor samples, Lymphocyte-activation gene 3 (LAG3), T-cell Immunoglobulin and Mucin-domain containing-3 (TIM3), and T cell immunoreceptor with Ig and ITIM domains (TIGIT) were upregulated and co-expressed in CD8+ T-cells." (PMID 38649887, 2024). "TIGIT, DNAM1, and CD96 (TACTILE) are known receptors for PVR in the immune system; binding of PVR to TIGIT suppresses tumor immunity while binding to DNAM1 promotes tumor immunity; binding to CD96 acts both to suppress and promote tumor immunity." (PMID 39156900, 2024). "Our study findings revealed that TIGIT expression in patients with HCC did not significantly correlate with tumor differentiation degree." (PMID 39540362, 2024). "This heightened immune cell presence is consistent with the observed reduction in exhaustion markers, such as LAG-3, TIGIT, and TIM-3, emphasizing the potential of BJIKT and pembrolizumab to mitigate T cell exhaustion and sustain a robust anti-tumor immune response." (PMID 39459546, 2024). "The disruption of TIGIT and CD73 activities promoted the function of iPSC-NK cells after adoptive transfer into intracranial patient-derived glioblastoma models, enhancing their innate cytolytic function against the tumor and ultimately eradicating the tumor." (PMID 39682724, 2024).
tumor (continued). "Recently, an engineered fusion protein, TIGIT-Fc-LIGHT, the linkage between the extracellular domain of TIGIT and the extracellular domain of TNFSF14, was reported to show anti-tumor activity in pre-clinical models, especially in those who were resistant to anti-PD-1 treatment." (PMID 38229100, 2024). "Importantly, this study sheds light on a novel mechanism through which TNBC cells exploit the CD155/TIGIT axis to rewire CD8 + T cell metabolism, thus creating an immunosuppressive milieu that supports tumor progression." (PMID 38216949, 2024). "This is in line with our observations, that immune cells in the TIME of HLA-G high MIBC – especially of evasion phenotype MIBCs- exhibited an upregulation of crucial immune checkpoint proteins like TIGIT, PD-L1, LAG3, and CTLA-4 on tumor cells (PD-L1) and immune cells (all proteins)." (PMID 39469714, 2024). "TIGIT is expressed on the surface of activated CD8+ T cells, memory and regulatory CD4+ T cells, NKs, Tregs, and follicular CD4+ T cells, and is also co-expressed with PD-1 on tumor-antigen-specific T cells and TILs in various cancer patients." (PMID 38257366, 2024). "The expression of TIGIT can be modulated by type 1 IFN and chemotherapy, while factors like microwave ablation, glucose deprivation, and hypoxic conditions can trigger its expression in tumor cells." (PMID 39684559, 2024). "The inhibitory receptors expressed on T cells, interacting with their corresponding ligands expressed on antigen-presenting cells or tumor cells, such as PD-1/PD-L1, CTLA-4/CD86, TIM-3/Galectin-9, TIGIT/CD155, and BTLA/HVEM, play important roles in regulating T cell functions." (PMID 39329729, 2024). "In light of these considerations, investigating the interplay between the CD155/TIGIT pathway and the metabolic behavior of CD8 + T cells in the context of TNBC holds promise for enhancing our understanding of tumor immune evasion and identifying potential therapeutic targets." (PMID 38216949, 2024). "Additionally, anti-PD1 combined with anti-HAVCR2, CTLA4, or TIGIT has been recently found to more effectively improve T-cell function, overcome resistance to anti-PD1 therapy, and eliminate tumour cells." (PMID 38297380, 2024). "In addition, IHC staining for exhaustion markers, including LAG-3, TIGIT, and TIM-3, was conducted on the tumor tissues to evaluate their impact on T cell exhaustion." (PMID 39459546, 2024). "Tex cells exhibit elevated inhibitory receptors (PD-1, CTLA-4, TIM-3, TIGIT, LAG-3), reduced antitumor cytokines (IFN-γ, IL-2, TNF), increased tumor-promoting chemokines, altered transcription factors (TCF1, T-bet, TOX), metabolic issues, and decreased proliferation and survival." (PMID 39717767, 2024). "Moreover, upon analyzing the TCGA database, which included 250 cancer patients treated with PD‐1/PD‐L1 inhibitors, the tumor microenvironment phenotype demonstrated a notable increase in PD‐1, TIM‐3, LAG3, TIGIT, T‐bet, and EOMES in tumors of obese patients." (PMID 38334504, 2024). "Analysis of CD8+ T cell clusters from spleen and tumour demonstrated that CD137 expressing clusters 2, 7 and 10 co-expressed a large number of markers related to activation/exhaustion (TIGIT, TIM3, PD-1, CD39, CD160)." (PMID 38986249, 2024). "Immunohistochemical analysis showed that the expression levels of CD47 and TIGIT in tumor tissues were significantly higher than those in normal brain tissues." (PMID 38404571, 2024). "Given the increase in B16F10 tumour-infiltrating DCs, co-stimulatory molecules on DCs, and activated (CD25+, TIGIT+) CD4 T cells, we predicted DC and T cell interactions might play a role in prolonging survival in Fgl2−/− mice." (PMID 38191799, 2024). "The ligands of TIGIT are CD112 and CD155, which are expressed by tumor cells and APC." (PMID 38612483, 2024).
tumor (continued). "In circulating CD8+ T cells from patients whose tumor achieved pCR, there was higher expression of cell adhesion molecules (CD62L, CCR8, CD49d, CD18), as well as TIGIT (which was also increased in intratumoral CD8+ T cells in pCR versus non-pCR pre-sotigalimab)." (PMID 38181044, 2024). "It was also found that blocking TIGIT signaling pathway of malignant tumors could significantly increase the expression of IFN-γ and TNF-α in tumor-specific CD8+ T cells and significantly improve the anti-tumor immune response." (PMID 38534423, 2024). "Combination of treatment with blockage of TIGIT and administration of sulfarotene in CRC mouse models resulted in activated NK cells with higher production of IFN-γ and decreased stemness signatures of tumor cells." (PMID 38543173, 2024). "We speculated that the communicative signal between TIGIT and NECTIN2 represented a crucial mechanism for LUAD tumor cells to establish the immunosuppressive microenvironment." (PMID 39474422, 2024). "HLX-301 are capable of binding to TIGIT and PD-L1, bringing CD8+ T cells to the tumor cells, which lead to an enhanced activation of CD8+ T cells by the increased interaction between HLA-I on the tumor cells and TCRs on T cells." (PMID 38257366, 2024). "Accordingly, it has been reported that TIGIT, but not other immune checkpoint molecules such as CTLA-4 and PD-1, is associated with NK cell exhaustion in tumor-bearing mice and pts with CRC and that the blockade of TIGIT restored NK cell antitumor activity." (PMID 39126041, 2024). "Blockade of TIGIT could prevent NK cell exhaustion and enhance the synthesis of IFN-γ by NK cells in tumor-bearing mice." (PMID 38543173, 2024). "By contrast, anti-CSF-1R treatment did not reduce the effects of anti-PD-L1 + anti-TIGIT treatment on tumour Treg cells, suggesting an alternative mechanism of action." (PMID 38418879, 2024). "mIgG2a anti-TIGIT, but not mIgG2b or Fc-inert anti-TIGIT, antibodies were capable of inducing tumour rejection when combined with Fc inert mouse anti-PD-L1." (PMID 38418879, 2024). "However, TIGIT-positive populations are high among NY-ESO-1 (TA; tumour antigen)-specific CD8+ T cells from PMBCs." (PMID 38893071, 2024). "Further exploration of treatments targeting other immune checkpoints, including LAG-3, VISTA, TIGIT, TIM-3, ADORA2, as well as therapies involving TIL (tumor-infiltrating lymphocytes), holds promise for delivering survival benefits to this subgroup of patients." (PMID 38469235, 2024). "Furthermore, the blockade or modulation of inhibitory receptors such as PD1, TIGIT, TIM3, KIRs (Killer-cell Immunoglobulin-like Receptors) on NK cells, which interact with MHC class I molecules on tumor cells." (PMID 39192980, 2024). "scRNAseq data analysis confirmed almost exclusive TIGIT expression on T- and NK cell populations, and no expression of TIGIT on tumor cells." (PMID 38438420, 2024). "In line with a recent study of tumor-infiltrating T cells, these results also suggest that inhibiting CD226 signaling by TIGIT might be one of the major mechanisms by which TIGIT imparts its immune regulation in self-reactive T cells." (PMID 38533515, 2024). "Analysis of spleens of mice isolated 13 days after transplantation confirmed the previously observed greater T-cell recruitment and increased expression of the exhaustion markers PD-1, TIGIT, LAG3 and TIM3, despite the reduced tumor burden in mice that received NFKBIE-ko cells." (PMID 38486128, 2024). "The interactions between tumor cells and altered myeloid cells within the TME are mediated by complex signaling pathways that become notably active following chemotherapy, particularly the TIGIT-PVR and MDK-SDC4 pathways." (PMID 39850495, 2024). "In contrast, PVR and TIGIT did not exhibit close proximity in lepidic tumor tissue but co-localized spatially in solid tissue." (PMID 39474422, 2024).